CD4 (CD4 molecule)
Diseases named in the same sentence as CD4 in open-access papers (continued):
Sharing a sentence is not in itself a finding about the gene and the disease.
tumor (continued). "Moreover, we observed a reduced expression of HLA class II molecules (CD74, HLA-DRA, HLA-DRB1, HLA-DMA), which might affect the number and function of CD4+ T lymphocytes in the tumor microenvironment." (PMID 36153593, 2022). "Notably, cognate CD4+ tumor-infiltrating lymphocytes (TILs) may directly kill MHC II+ tumor cells or limit tumor growth by promoting the functional conversion of protumor M2 macrophages to antitumor M1 macrophages." (PMID 35703176, 2022). "CD4+ and CD8+ T cells could be induced by vaccination with new epitopes encoded by these genes, thus improving the efficacy of radiation therapy, disregarding their ineffectiveness in preventing tumor growth." (PMID 36263174, 2022). "Although effective immunotherapy promotes the killing of cancer cells by cytotoxic T cells, CD4+ helper T cells, regulatory T cells (Tregs), effector T-cells, macrophages, and neutrophils are also important immune factors that can either promote or block tumor development." (PMID 35203532, 2022). "Additionally, they observed that TLS were significantly associated with higher CD8:CD4 T-cell ratio in the tumor periphery, but not within the tumor center." (PMID 36551547, 2022). "Additionally, the analysis by the TIMER database showed that PD-L2 expression was negatively correlated with tumor purity and positively associated with the infiltrating levels of B cells, CD8+T cells, CD4+ T cells, macrophages, neutrophils, and dendritic cells." (PMID 35756621, 2022). "Interestingly, depletion of CD4+ T cells reduced tumor growth in both Asm-WT and Asm-KO mice." (PMID 36426850, 2022). "Research from other tumor types suggests that EMT progression is mediated by immune regulation; specifically, cytokines such as TGF-beta, IL-10, and immune cell populations such as tumor-associated macrophages and some subsets of CD4+ and CD8+ T cells appear to be critical to this regulation." (PMID 36139624, 2022). "miRNAs may be a tool to address the challenges that CAR–T-cells face, because miRNAs can control tumor antigenicity, amplify T-cell responses, expand CTLs and anti-tumorigenic CD4+ T cells, increase T-cell infiltration into the TME, and counteract the effects of immunosuppression." (PMID 36248881, 2022). "The typical cancer vaccines involve in exogenously administrating tumor antigens with adjuvants, which could be delivered to antigen‐presenting cells (APCs), predominantly dendritic cells (DCs), inducing strong CD4+ T cells and cytotoxic T lymphocytes (CTLs) responses to eliminate tumor cells." (PMID 35593226, 2022). "CD4 T cells infiltrating the TME may help tumor tissues escape immune surveillance." (PMID 36497288, 2022). "(2010) further demonstrated the cytolytic potential of CD4+ cyTreg in anti-tumor responses using two-photon microscopy in explanted tumor draining lymph nodes (LN) to show that DC death only occurred when perforin sufficient Foxp3+ Treg were present and in the presence of tumor antigens." (PMID 35493508, 2022). "Additionally, tumor-infiltrating CD8+ Tregs show synergistic immunosuppression with CD4+ Tregs." (PMID 35804964, 2022). "Moreover, BTN3A2 expression is a remarkable positive correlation with invading levels of tumor purity, B cells, neutrophils, CD4+ T cells, dendritic cells, macrophages, and CD8+ T cells in LUAD, and B cells and dendritic cells were linked with a good prognosis of LUAD." (PMID 35873496, 2022). "We speculate that a significant drop in CD4+ T helper cells might be responsible for the impaired cytolytic activity of NK cells in advanced tumor stages when immunological tumor control has evidently failed, and the tumor load has increased." (PMID 36428793, 2022). "Besides, studies showed that MHC class I-restricted tumor-specific TCR could be harnessed to program CD4+ T cells with antitumor effector functions." (PMID 35928827, 2022). "Moreover, the Dok-3 loss–induced tumor invasion in ApcMin/+ mice required CD4+ and CD8+ T lymphocytes, but not B lymphocytes." (PMID 36970719, 2022).
tumor (continued). "Therefore, we sought to identify cell-surface markers that enrich for tumor-reactive CD4+ Th cells." (PMID 35439168, 2022). "The effect of CD4+ T cells against tumor cells could be direct or indirect." (PMID 36139357, 2022). "Interestingly, a study reported that 4-1BB agonist treatment induces a subset of CD4+Foxp3+ Tregs to eliminate virus-induced tumor cells in mice, and the addition of 4-1BB expression in CAR T cells with an intracellular CD28 costimulatory domain improves their proliferation and cytotoxicity." (PMID 35917188, 2022). "Cells of this phenotype mediate the graft versus tumour effect in xenograft studies of cord blood T-cells, and we are testing the use of granulocytes to stimulate such T-cell expansion after cord blood transplant, since immune reconstitution is predominantly otherwise CD4-biased." (PMID 35465327, 2022). "Moreover, treatment with SGLT2 inhibitor or 2’3’-cGAMP alone or in combination promoted tumor infiltration by CD45+CD4+ and CD45+CD8+ T cells, which may explain their synergistic effect in suppressing tumor growth." (PMID 35662245, 2022). "Additionally, we checked CD4+ PD-1− TILs infiltration on both sides of tumor." (PMID 36513720, 2022). "Thus, it is tempting to speculate that senescent CD4+ T cells and cytokines produced by them, among other components, could play a critical role in promoting an environment more conducive for tumor development and growth." (PMID 35821823, 2022). "Interestingly, during tumour development, CD4+T cells may progressively transdifferentiate into IL-17A+ FOXP3+ and ex-Th17 IL-17A- FOXP3+ T cells." (PMID 36569832, 2022). "Adoptive transfer of tumor-specific CD4+ T cells could mitigate metastasis." (PMID 35784297, 2022). "Therefore, the T cells’ help from CD4+ T cells could support the eradication of the tumor and the recruitment of more CD8+ T cells by setting an inflammatory stimulus." (PMID 36077730, 2022). "Therefore, we investigated CD4 phenotypes before and after the co-culture with tumor cells." (PMID 35606862, 2022). "However, in recent years, some studies have shown that some TIL subtypes, such as CD4+ T cells (CD4+ regulatory T cells, Tregs), may be one of the main factors that have an immunosuppressive role within the tumor." (PMID 35574386, 2022). "Examination of tumor specimens from our case series showed that miR-18a high ER+ tumors had a dense lymphocyte infiltrate when compared to miR-18a low tumors but expressed a higher CD4/CD8 ratio and the M2 macrophage marker CD206, along with the invasive marker MMP9." (PMID 35626709, 2022). "Taking CD4+ Treg cells and CD8+ cytotoxic T cells as examples, Treg cells derived from tumor tissues showed higher expression of LAYN, LGALS1 and TNFRSF1B, and cytotoxic T cells derived from tumor tissues showed higher expression of TNFRSF9 (encoding 4-1BB), LAYN and CTLA4." (PMID 36104333, 2022). "However, few of the mice were tumor-free, indicating that the tumor-specific CD4+ T cells may have been exhausted, akin to CD8+ T cells, as antigens persisted." (PMID 35784297, 2022). "Moreover, the results of HE staining reflected that the inflammatory infiltration of tumor tissue was promoted after exosome treatment; while the immunohistochemical staining of the tumor section showed that, after exosome treatment, CD4+ and CD8+ T cell infiltration was alleviated." (PMID 35461336, 2022). "Therefore, the presence of CD4 marker within local tumor microenvironment might implicate a wide range of scenarios." (PMID 35963999, 2022). "However, compared to MDSCs from the tumor-bearing control group, MDSCs in the cryo-thermal therapy group significantly decreased Th1 differentiation and inhibited the expression of granzyme B in CD4+ T cells." (PMID 36389684, 2022).
tumor (continued). "In mouse tumor models, B-MFs promote shrinkage of the tumor-infiltrating IFNγ+ CD4 T cell pool and increase cancer progression and metastasis, suggesting that this cancer-induced transdifferentiation pathway is functionally relevant and hence could serve as an immunotherapeutic target." (PMID 36104343, 2022). "In addition, flow cytometry and immunofluorescent analysis of tumor samples demonstrated a significant reduction in the percentage of CD4+ T cells along with Arginase-1+ cells/macrophages in the tumors in the combination treatment arm than in the nivolumab-alone arm." (PMID 36212401, 2022). "While 4T1-IL-6-KO tumor growth was similar to the control, the reduced IL-6 significantly expanded the total CD4+ Th population and Th17 in tumors, while Th22 and MDSC were reduced in all tissues; this suggests that clinical IL-6 depletion combined with immunotherapy could improve outcomes." (PMID 36142210, 2022). "Interestingly, we found that Tr1 cells are present in high frequencies since early in the tumor onset process, comprising over 20% of the CD4+ population 1 week after the tumor induction, while the cTreg fraction comprised <5% of the CD4+ T cell subset at the same time point." (PMID 35860556, 2022). "Thus, transgenic CD4+ T cells co-expressing class I–restricted tumor antigen–specific TCR and CD8αβ have shown comparable cytotoxic properties to engineered CD8+ T cells and were most potent by activating multiple transcriptional programs associated with enhanced antitumor function." (PMID 35008422, 2022). "Moreover, recent studies in the literature suggest that cDC2 may be involved in presenting tumor-derived antigens to CD4+ T cells, which assist and support CD8+ T cells in their antitumor activity." (PMID 35757002, 2022). "Notably, TAPBP was significantly correlated with most immune cells (n=16) and was positively correlated with CD8 T cells, activated memory CD4 T cells and activated NK cells, which could kill tumor cells." (PMID 36311733, 2022). "Moreover, neoantigen specific CD4+ T cells were able to produce Th1 cytokines, kill irradiated tumor cells and promote epitope spreading, which highlight the critical implication of RT as a combinatorial partner to neoantigen vaccination to improve vaccine efficacy." (PMID 35008422, 2022). "Therefore, using PD-1 and ICOS to enrich for tumor-reactive CD4+ Th cells prior to TIL expansion may be a way to increase the clinical success of adoptive T cell therapy." (PMID 35439168, 2022). "Interestingly, i.p. inoculation of EAC mice with a low dose of P.pavonica extract and high dose of J.rubens extracts recorded the highest increase in the percentage of splenic helper CD4+ T cells subset population (86.5% and 60.6%, respectively) compared to naïve tumor mice (13.8%)." (PMID 35999584, 2022). "Indeed, IT delivery of TransCon TLR7/8 Agonist led to an increase in activated CD8 and CD4 T cells in peripheral blood and tDLN, which may contribute to systemic anti-tumor responses." (PMID 36123697, 2022). "Likewise, CD4 Tregs present at the tumor site could inhibit the antitumor effect of both CD4 and CD8 effector cells through interaction with antigen-presenting TAMs." (PMID 35903540, 2022). "As expected, flow cytometry analyses of CD4+ T cells from central draining lymph nodes of the GB mice treated with different strategies showed that either intracranial or intravenous therapy with KO PC seem to be effective to activate the anti-tumor T cell responses." (PMID 35419364, 2022). "Interestingly, activin subunit expression correlated with CD4+ T-cell infiltration, and the correlation with higher overall survival was exclusively seen in tumors with high CD4+ T-cell infiltration, pointing towards a role of activin in the tumor immune response in AEG/ASs." (PMID 36064338, 2022).
tumor (continued). "In addition, analysis of 22 immune cell types from The Cancer Genome Atlas (TCGA) data showed EGFR L858R was correlated with low level of CD8 T cells, activated CD4 memory T cells and elevated level of macrophage M2 suggesting an inhibited tumor microenvironment (TME)." (PMID 36505399, 2022). "The expression of VISTA on CD4+ T cells may indicate regulation of tumor immunity." (PMID 35122478, 2022). "PDIA3 is associated positively with the degree of infiltration of CD4+ T cells, CAF, MDSC, neutrophils, and macrophages in most cancers, indicating that PDIA3 is most likely to affect the development and prognosis of cancers by shaping the tumor microenvironment." (PMID 35401558, 2022). "Compared with Cluster 2, the infiltration of CD4+ T cells and follicular helper T cells (Tfhs) that promote tumor immunity was lower in Cluster 1 (both P < 0.01), while the infiltration of nTreg cells and iTreg cells that inhibit tumor immunity was higher in Cluster 1 (P = 0.049, 0.000)." (PMID 36494419, 2022). "Therefore, and since we observed no significant increase of Tgfb1 mRNA expression or of FoxP3+CD4+ Tregs in βΑ tumors, we wondered whether Activin-A stimulates tumor growth by promoting IL4 signaling." (PMID 35580932, 2022). "However, some studies have recently demonstrated that CD4+ T cells are critical mediators of peripheral tolerance and immunosuppression and may play a central role in anti-tumor immunity." (PMID 35711924, 2022). "Anti-tumour immunity was observed against B16 tumours expressing either constitutive or IFNγ inducible HLA-DP*0401 suggesting that the CD4 T cell response may exert both direct and indirect effects upon the tumour to promote inflammation and MHCII upregulation." (PMID 36544781, 2022). "For instance, inhibition of RA receptors has been shown to increase the efficacy of anti-tumor DC vaccines in a murine melanoma model through the suppression of tumor-infiltrating Treg cells and up-regulation of tumor-infiltrating, interferon-γ-secreting CD4+ and CD8+ T cells." (PMID 35299840, 2022). "Interestingly, naive CD4+ and CD8+ T cells displayed increased expression of the memory-associated marker CD45RO after 48 and 72 h of coculture with MDA-MB-468 tumor cells in the presence of DuoBody-CD3x5T4, indicating a shift of the naive T-cell subsets toward a memory-like phenotype." (PMID 36271507, 2022). "Consequently, this kind of metabolism modulation breaks the balance of the immune state in the tumor, resulting in an enhanced immunosuppressive effect by promoting the CD4+ CD25+ regulatory T (Treg) cell metabolic profiles and maintaining the acidity of the TME." (PMID 35265521, 2022). "Therefore, we wondered whether some subtypes of CD4+ or CD8+ T cells may alter the anti‐tumour efficacy with anti‐PD1 or PDL1 treatment." (PMID 36336787, 2022). "Besides, the levels of CD8 + T cells and activated memory CD4 T + cells which could inhibit the tumor progression were significantly increased in GC with low-risk score and they have a better prognosis." (PMID 35372408, 2022). "However, accumulating evidence has shown that some cytotoxic CD4+ T cells directly kill tumour cells and may play a key role in anti-tumour immunity." (PMID 36159866, 2022). "Hence, a better understanding of tumor-specific CD4+ T cells and regulation of their function in adoptive cell therapy may contribute to the development of effective cancer immunotherapies." (PMID 35784297, 2022). "In addition, there were frequent overlaps of clonotypes between CD4+ and CD8+ Teff cells, which made us speculate that the CD4+ Teff cells were also involved in tumor killing." (PMID 36532049, 2022). "Further transcriptional profiling of DP CD4+ TILs may uncover additional biomarkers and pathway factors that may be therapeutically targeted to selectively reinforce or improve tumor antigen–specific DP Th cell bioactivity within the TME to benefit patient outcomes." (PMID 35703176, 2022).
tumor (continued). "Also, the expression levels of DFNA5 were pronounced association with CD8 + T cells in fourteen tumor types, B cell in fourteen tumor types, macrophages in eighteen tumor types, neutrophils in twenty tumor types, CD4 + T cells in nineteen tumor types and dendritic cells in thirty-one tumor types." (PMID 35248047, 2022). "In contrast, CD4+ depletion, particularly depletion of the CD25+ subset (inclusive of Treg), seemed to cause a suppression of tumor growth (TGI 22% and 42% respectively), suggesting a potential key role of Tregs in promoting tumor growth by suppressing tumor immunity." (PMID 35228603, 2022). "Additionally, TGF-β is known to convert CD4+ T- cells into Tregs to suppress anti-tumor immunity." (PMID 36578789, 2022). "Consistent with this is the finding that ROS, including tumor-derived ROS, can trigger the accumulation of SUMO-specific protease 3 (SENP3), a protein crucial for deSUMOylation of BACH2, in Tregs, which results in the repression of genes associated with effector CD4+ T cells." (PMID 35040434, 2022). "Because our analyses of tumor-bearing mice treated with cGAMP also revealed an increased frequency of IL-9-producing CD4 T cells in the tumor microenvironment, we finally evaluated the contribution of other CD4 T cell-derived cytokines (IL-9, IL-17, and IL-4) to the anticancer effects of cGAMP." (PMID 35091453, 2022). "However, in several experimental models as well as in cancer patients, it has been shown that CD4+ T cells can also mediate antitumor immunity either directly by killing tumor cells or indirectly by activating innate immune cells or by reducing tumor angiogenesis." (PMID 36159781, 2022). "Hence, a better understanding of cytotoxic CD4- T cell-mediated tumor regression could provide an alternative choice for patients exhibiting suboptimal or no response to CD8+ T cell-based immunotherapies." (PMID 35784297, 2022). "Regarding intraepithelial tumoral infiltration, dense CD4+ cell infiltrate associated with poor tumor differentiation (phi = 0.45, p = .040), and higher CD4+ (phi = 0.46, p = .046) and CD20+ infiltration (phi = 0.69, p = .003) correlated with advanced tumor stage." (PMID 36177667, 2022). "Indeed, oxaliplatin treatment results in increased expressions of TERT, COA-1 and mesothelin tumor antigens, which may give rise to immunogenic peptides recognized by CD4+ T cells." (PMID 35008422, 2022). "Moreover, since tumor growth was inversely correlated only with PAt conventional CD4 +cells, additional targeting of the Treg remaining after double treatment, might improve the success of therapy." (PMID 35338089, 2022). "Furthermore, isolation of the DP PD-1+ICOS+ cell population could be used to enrich for tumor-reactive CD4+ Th cells for adoptive T cell therapy approaches." (PMID 35439168, 2022). "In this study, we found that a high frequency of CD4+FoxP3+Helios+ Tregs in blood was associated with shorter DFS, suggesting the potential role of this highly immunosuppressive Treg subset in inhibiting anti-tumor immune responses, and consequently worsening clinical outcomes." (PMID 35655158, 2022). "The tumor antigens that drive protective T cell responses have been elusive until about 10 years ago when it was discovered that somatic mutations that accumulate in cancers can stimulate both CD8 and CD4 T cell responses and are associated with clinical response to ICB therapy." (PMID 36077528, 2022). "In addition to the typical expression of CD25, CD4, and FOXP3, Treg cells express a number of chemokine receptors and surface molecules, such as CTLA4, PD-1, and TIGIT, which are linked to anti-tumor immunity and may make them a direct target for ICI therapy." (PMID 35967424, 2022). "By administering either inactivated resected tumor lysates or allogeneic tumor-cell lysates with additional components such as adjuvants and cytokines, these cancer vaccines could present epitopes of tumor antigens to activate both CD4+ and CD8+ T cells in the human body." (PMID 35456701, 2022).